RN7SL507P (RNA, 7SL, cytoplasmic 507, pseudogene)
Gene: Miscellaneous RNA gene on chromosome 17 (44,290,856 to 44,291,151, reverse strand). Ensembl gene ENSG00000239702.
Homologues: Orthologues: chimpanzee Metazoa_SRP (99% identical), macaque Metazoa_SRP (95% identical). Paralogues in human: RN7SL1 (88% identical), RN7SL2 (87% identical), RN7SL3 (85% identical), RN7SL296P (84% identical), RN7SL126P (82% identical), RN7SL178P (82% identical), RN7SL45P (82% identical), RN7SL597P (82% identical), RN7SL660P (82% identical), RN7SL478P (82% identical), RN7SL664P (82% identical), RN7SL712P (82% identical), and 702 more.